ADPRS (ADP-ribosylserine hydrolase)
Description:
ADP-ribosylhydrolase that preferentially hydrolyzes the scissile alpha-O-linkage attached to the anomeric C1'' position of ADP-ribose and acts on different substrates, such as proteins ADP-ribosylated on serine and threonine, free poly(ADP-ribose) and O-acetyl-ADP-D-ribose. Specifically acts as a serine mono-ADP-ribosylhydrolase by mediating the removal of mono-ADP-ribose attached to serine residues on proteins, thereby playing a key role in DNA damage response. Serine ADP-ribosylation of proteins constitutes the primary form of ADP-ribosylation of proteins in response to DNA damage. Does not hydrolyze ADP-ribosyl-arginine, -cysteine, -diphthamide, or -asparagine bonds. Also able to degrade protein free poly(ADP-ribose), which is synthesized in response to DNA damage: free poly(ADP-ribose) acts as a potent cell death signal and its degradation by ADPRHL2 protects cells from poly(ADP-ribose)-dependent cell death, a process named parthanatos. Also hydrolyzes free poly(ADP-ribose) in mitochondria. Specifically digests O-acetyl-ADP-D-ribose, a product of deacetylation reactions catalyzed by sirtuins. Specifically degrades 1''-O-acetyl-ADP-D-ribose isomer, rather than 2''-O-acetyl-ADP-D-ribose or 3''-O-acetyl-ADP-D-ribose isomers.
Synonyms: ADPRHL2; ARH3; FLJ20446; CONDSIAS
Tractability: Small molecule: a structure with a bound ligand is known. PROTAC: ubiquitination databases record sites on it.
Target class: Enzyme; Hydrolase
Gene: Protein-coding gene on chromosome 1 (36,088,878 to 36,093,932, forward strand). Ensembl gene ENSG00000116863.
Subcellular location: Nucleus; Cytoplasm; Chromosome; Mitochondrion matrix
Subcellular location (Human Protein Atlas): Nucleoplasm
Pathways (Reactome):
DNA Repair: POLB-Dependent Long Patch Base Excision Repair
Gene Ontology:
Molecular function: ADP-ribosylserine hydrolase activity; hydrolase activity, hydrolyzing O-glycosyl compounds; magnesium ion binding; O-acetyl-ADP-ribose deacetylase activity; poly(ADP-ribose) glycohydrolase activity; protein binding
Biological process: cellular response to superoxide; DNA repair; peptidyl-serine ADP-deribosylation; base-excision repair, gap-filling; negative regulation of necroptotic process
Cellular component: chromosome; cytoplasm; mitochondrial matrix; mitochondrion; nucleoplasm; nucleus; site of DNA damage
Genetic constraint (gnomAD): Loss-of-function variants: 26 observed, 31.25 expected, observed/expected ratio (o/e) 0.83, 90% interval 0.61 to 1.15. The upper end of that interval is the gene's LOEUF score, 1.15, which puts it in group 5 of 6, group 1 being the genes least tolerant of losing a copy. Missense variants: 482 observed, 464.62 expected, observed/expected ratio (o/e) 1.04, 90% interval 0.96 to 1.12. Synonymous variants: 225 observed, 193.36 expected, observed/expected ratio (o/e) 1.16, 90% interval 1.04 to 1.3.
Homologues: Orthologues: chimpanzee ADPRS (99% identical), macaque ADPRS (98% identical), guinea pig ADPRS (94% identical), rabbit ADPRS (93% identical), pig ADPRS (92% identical), rat Adprs (92% identical), mouse Adprs (91% identical), tropical clawed frog adprs (53% identical), zebrafish adprs (53% identical).
Diseases named in the same sentence as ADPRS in open-access papers:
ADPRS is named in the same sentence as 33 diseases in open-access papers, as found by Europe PMC text mining. Sharing a sentence is not in itself a finding about the gene and the disease.
ADPRS shares sentences with these, for which no sentence is quoted: Ataxia (8 papers); neurodegenerative disease (6); cancer (3); osteosarcoma (3); developmental delay (2); glioblastoma (2); tumor (2); axonal neuropathy (1); brain infarction (1); Cerebellar Ataxia (1); Cerebellar atrophy (1); CONDSIAS) (1); craniofacial microsomia (1); genetic disorder (1); hearing loss (1); hepatocellular carcinoma (1); inherited neurodegenerative disorder (1); Intellectual disability (1); metabolic disease (1); neuroblastoma (1); neuropathy (1); Okur-Chung neurodevelopmental syndrome (1); ovarian carcinoma (1); peripheral neuropathy (1); progressive ataxia (1); prostate carcinoma (1); psoriasis (1); quadriplegia (1); retinitis pigmentosa (1); Seizure (1).
A further 3 diseases each share a sentence with ADPRS in 1 paper.